SP1 (Sp1 transcription factor)
Diseases named in the same sentence as SP1 in open-access papers (continued):
Sharing a sentence is not in itself a finding about the gene and the disease.
ovarian carcinoma (continued). "Using chromatin immunoprecipitation experiments we have shown that Sp1 is able to bind this site in JAM and A2780 ovarian cancer cell lines in vivo." (PMID 26840454, 2016). "The hypoxia-inducible factor 2α (HIF2α)–SP1 complex activated coagulation factor VII promoter in OCCC and estrogen receptor α also form complexes with SP1 in other types of ovarian cancer 31,32." (PMID 25060396, 2014). "It has been observed that hsa-miR-335-5p acts as a tumor suppressor when it targets Bcl-w in ovarian cancer cell lines or SP1 and Bcl-w in GC, where it suppresses cell invasion but not proliferation." (PMID 39125490, 2024). "Among these transcription factors, SP1 is overexpressed in ovarian cancer, while there are no prior studies on the expression of NF-YA and XBP-1 in ovarian cancer (OncomineTM database)." (PMID 29262583, 2017). "The effect of DIG-MSK was also evident on the loading of Sp1 on the other gene promoters: XIAP whose down-regulation can induce cell death, CRABP1, a gene involved in the development of ovarian carcinoma, and MDK that is a marker in ovarian cancer." (PMID 25110883, 2014). "Due to the fact that WT1 gene has been shown to be transcriptionally regulated by some upstream transcriptional factors like Sp1, PAX2, PAX8 and PEA3, it is worthwhile to further analyze the expression status of these upstream molecules in ovarian cancer specimens obtained from this population." (PMID 16606472, 2006). "Therefore, we hypothesize that the cytotoxic effects of 6RK73 in ovarian cancer cells may occur through a UCHL1-independent mechanism, potentially involving suppression of the AKT1/Sp1/c-Myc signaling axis." (PMID 41584043, 2026). "Compared with control exosomes, exosomes derived from ETS1-overexpressing ovarian cancer cells (LV-ETS1 Exos) stimulated the polarization of more macrophages toward the M2 phenotype (CD163 marker), as well as the production of more CXCL5 and CCL2 in macrophages, via integrin αvβ5/AKT/Sp1 signaling." (PMID 36477408, 2022). "Western blot analyses indicated that Sp1 could significantly elevate the expression levels of survivin as well as XIAP, while KLF12 had the opposite effects compared to Sp1 and suppressed survivin and XIAP expressions in both ovarian cancer cell lines." (PMID 28095864, 2017). "A GC-rich/Sp1 promoter binding region in important in the regulation of GCS expression; furthermore, doxorubicin can induce the activation of Sp1 and the upregulation of GCS and apoptosis in the leukemia drug-resistant cell line HL-60/ADR in addition to an ovarian cancer cell line." (PMID 23133636, 2012). "In this study, we observed that 6RK73, as a potential anti-cancer agent, significantly inhibited ovarian cancer cell growth and cell cycle progression by attenuating AKT1/ Sp1/c-Myc signaling, independent of UCHL1 inactivation." (PMID 41584043, 2026). "Finally, we transfected AKT1 into ovarian cancer cells with or without 6RK73 treatment and found that AKT1 overexpression reactivated AKT1/Sp1/c-Myc signaling and reversed 6RK73-induced growth suppression." (PMID 41584043, 2026).
colon carcinoma (67 papers, 2010 to 2025). "Sp1, a transcription factor involved in early development, is implicated in colon cancer cell growth and progression." (PMID 32517689, 2020). "For example, SP1 regulating most of the upregulated DEmiRs has been associated with colon tumor adhesion, migration and invasion." (PMID 31500382, 2019). "It has previously been reported that high Sp1/Sp3 binding to the urokinase receptor predicted poor survival of colon cancer patients and high expression of Sp1 was associated with an increased depth of invasion in another set of colon cancer patients." (PMID 26673922, 2015). "In Ewing sarcoma, HDAC6 modulates acetylation of SP1 and its binding to activating promoter regions, and a reduction in SP1 acetylation was shown to result in loss of promoter binding associated with cell cycle arrest in colon cancer." (PMID 39800760, 2025). "The ligand-induced and PPARƔ/Sp1-dependent activation of p21 in pancreatic thyroid and colon cancer cells involved the same proximal (−124 to −60) GC-rich sites in the p21 gene promoter." (PMID 39858066, 2025). "Drug resistance of colon cancer cells can be effectively reversed by transfection of miR-125b-5p mimics or silencing of Sp1 or CD248 genes." (PMID 39867908, 2024). "As we knew that the transcription factors always had a correlated expression with their downstream genes, thus we used the GEPIA database to explore the expression correlation between GSTM2 and CTCF, RAD21, SP1 in colon cancer." (PMID 36263204, 2022). "Eventually, we identified RAD21 and SP1 as potential transcription factors of GSTM2 in colon cancer." (PMID 36263204, 2022). "The results showed that there were significantly negative expression correlations between the GSTM2 expression with the three transcription factors, which suggested CTCF, RAD21, SP1 as potential transcription factors of GSTM2 in colon cancer." (PMID 36263204, 2022). "In colon cancer, SP1 induces drug resistance to 5‐Fu via modulating the members of the Mitogen‐actived protein kinase (MAPK) signaling pathway." (PMID 35924788, 2022). "MiR-133a is also able to inhibit cellular proliferation and colony formation by targeting SP1 protein that binds to IGF1-R promoter blocking IGF-1 involved in colon cancer progression." (PMID 34575979, 2021). "Analysis of differentially methylated loci established FOSL1 and SP1/2/3 binding motifs as highly ranked for hypomethylated and hypermethylated genes respectively, in a side-independent manner within colon cancers." (PMID 32293332, 2020). "Sp1 maintains the expression of fas directly and also has been shown to regulate Srebp-1c in colon cancer." (PMID 31614732, 2019). "It has been previously reported that aspirin inhibits VEGF and tumor growth by direct downregulation of Sp1 in colon cancer cells." (PMID 30693272, 2018). "Recently, we identified the core promoter region of the β4GalT4 gene and showed that the Specificity protein 1 (Sp1)-binding site (−88/−76) in the 0.17 kb core promoter region is critical for the promoter activity in SW480 human colon cancer cells." (PMID 30082623, 2018). "Mechanistic studies suggest that sulindac sulfide induces reactive oxygen species (ROS) which in turn downregulates expression of Sp1, Sp3 and Sp4 in colon cancer cells." (PMID 26673922, 2015). "miR-22 expression inhibits cell migration and invasion via targeting transcription factor Sp1, while it suppresses colon cancer cell migration and invasion by inhibiting the expression of T-cell lymphoma invasion and metastasis 1 (TIAM1)." (PMID 25938468, 2015). "Further, the expression of Sp1, Sp3, and Sp4 was also downregulated by high AA in K562 cells, as was observed in colon cancer cells." (PMID 23626851, 2013).
colon carcinoma (continued). "We further assessed the involvement of the pro-oncogenic specificity protein (Sp) transcription factors Sp1, Sp3, and Sp4 in the antileukemic effect of high AA because high AA exhibits anticancer activity towards colon cancer cells." (PMID 23626851, 2013). "We further assessed the involvement of Sp1, Sp3, and Sp4 in the antileukemic effect of high AA because high AA exhibits anticancer activity towards colon cancer cells, which is due in part to downregulation of Sp transcription factors and Sp-regulated genes." (PMID 23626851, 2013). "Results of this study has identified a novel pathway for aspirin-induced effects on Sp1, Sp3 and Sp4 in colon cancer cells, and current studies are focused on specific enzymes and pathways associated with the effects of aspirin on zinc homeostasis." (PMID 23110215, 2012). "Colon cancer cell growth inhibition was accompanied by downregulation of Sp1, Sp3 and Sp4 proteins and decreased expression of Sp-regulated gene products including bcl-2, survivin, VEGF, VEGFR1, cyclin D1, c-MET and p65 (NFκB)." (PMID 23110215, 2012). "Since NFκB (p65) and the β-catenin promoters contain GC-rich Sp binding sites, we used RNAi to determine the role of Sp1, Sp3 and Sp4 in regulation of p65, p50 and β-catenin in colon cancer cells." (PMID 23110215, 2012). "In summary, we have shown that the anticancer activity of BA in colon cancer cells is due, in part, to downregulation of Sp1, Sp3, Sp4 and Sp-regulated prooncogenic gene products." (PMID 21864401, 2011). "Additionally, circ_0017552 was shown to enhance colon cancer cell proliferation through SP1-induced NET1 expression." (PMID 40652278, 2025). "Moreover, in HT-29 colon cancer cells, quercetin–resveratrol combination treatment reduced the proteins SP1, SP3, and SP4, transcription factors known to be overexpressed in colon cancer." (PMID 37373289, 2023). "Furthermore, CD44 and the transcription factor SP-1 was probably involved in the inhibitory effect of CBS/H2S axis on colon cancer cells." (PMID 35172821, 2022). "Thus, we conclude that endogenous H2S/polysulfide biosynthesis by 3-MST in colon cancer cells promotes CyR61 mRNA induction, most likely through Sp1 sulfhydration, and through the activation of S1PR, ATF1 and CREB." (PMID 36113340, 2022). "Wnt activates β-catenin and induces the formation of a complex with SP1 that binds the promoter of the Axin2 gene to activate the transcription in colon cancer, and Axin2 expression is quickly suppressed following dephosphorylation of LRP6 in the lipid raft by a porcupine inhibitor." (PMID 33430034, 2021). "For example, miR-760 inhibits the tumorigenesis of colon cancer via regulating SP1." (PMID 29654167, 2018). "On the other hand, other reports have shown that aspirin inhibits tumor growth through direct downregulation of Sp1 in colon cancer cells; this discrepancy may be due to different gene regulation systems of Sp1 in different cells." (PMID 30693272, 2018). "Interestingly, another report states that ascorbic acid leads to ROS-dependent repression of transcription factor Sp1 and Sp-regulated genes in colon cancer cells." (PMID 28225083, 2017). "WIN55212-2 also increased PTPN6 expression and protein phosphatase A2 (PPA2) activity in SW480 colon cancer cells and reduced the expression of the pro-tumorigenic transcription factors, specificity protein 1, 3, and 4 (SP1, SP3, and SP4)." (PMID 29066974, 2017).
colon carcinoma (continued). "Interestingly, the colon cancer cell line RKO expressed high levels of SHIP2 and Sp1, suggesting a different expression pattern of SHIP2 and Sp1 in gastric and colon cancer cells." (PMID 28117748, 2017). "Moreover, in HT-29 colon cancer cells, treatment with quercetin in combination with resveratrol resulted in decreased SP1, SP3 and SP4 proteins, transcription factors known to be overexpressed in colon cancer." (PMID 27681738, 2016). "Taken together, these data suggest that knockdown of KV9.3 inhibits proliferation in colon carcinoma and lung adenocarcinoma cell lines and may be regulated by Sp1." (PMID 25924237, 2015). "This study demonstrates that sulindac sulfide, the active metabolite of sulindac which is known to exhibit anti-neoplastic activity in human and experimental models of colon cancer, also downregulates Sp1, Sp3, Sp4 and pro-oncogenic Sp-regulated genes in colon cancer cells." (PMID 26673922, 2015). "In addition, celecoxib, and other COX-2 inhibitors such as nimesulide and NS-398 can induce proteasomal degradation of Sp1 and decrease Sp1 phosphorylation, in multiple colon cancer cell lines, which is required for its transcriptional activity." (PMID 23875171, 2013). "Thus, pharmacologic doses of aspirin that give low mM serum concentrations can be accompanied by >30-fold higher concentrations of salicylate which are more than sufficient to inhibit colon cancer cell growth and decrease Sp1, Sp3, Sp4 and Sp-regulated genes." (PMID 23110215, 2012). "In summary, this study demonstrates that aspirin induces caspase-dependent proteolysis of Sp1, Sp3 and Sp4 proteins in colon cancer cells and tumors and, this was accompanied by downregulation of several Sp-regulated genes involved in cell proliferation, survival and angiogenesis." (PMID 23110215, 2012). "Since overexpression of ZBTB10 and antisense-miR-27a also decreases expression of Sp1, Sp3, Sp4 and Sp-regulated genes in colon cancer cells, the mechanism of action of BA in RKO cells is linked to disruption of miR-27a:ZBTB10 as previously reported for CDODA-Me and GT-094 in colon cancer cells." (PMID 21864401, 2011). "Thus, our current working hypothesis is that endogenously generated H2S (most likely via intermediary polysulfides) induces CyR61 mRNA through Sp1 sulfhydration in colon cancer cells." (PMID 36113340, 2022). "Consequently, the up-regulation of RAD21 and SP1 might be the second probable reason for the down-regulated expression of GSTM2 in colon cancer." (PMID 36263204, 2022). "Therefore, of the three genes, the expression of RAD21 and SP1 in colon cancer matched the results of correlation analysis, so that RAD21 and SP1 might be the potential upstream transcription factors of GSTM2 in colon cancer." (PMID 36263204, 2022). "Sp1 and also Sp3 and Sp4 are highly expressed in cancer cells and in this study, we have used results of RNA interference (RNAi) to show that the three TFs individually play a role in the growth, survival and migration/invasion of breast, kidney, pancreatic, lung and colon cancer cell lines." (PMID 26967243, 2016). "Colon cancer patients on low dose aspirin therapy (75 mg/d; ca. 1 mg/kg/d) would exhibit maximum average serum concentrations of salicylate (6.8 mM) and aspirin (0.21 mM) sufficient to inhibit colon cancer cell growth and decrease expression of Sp1, Sp3, Sp4 and Sp-regulated genes." (PMID 23110215, 2012). "3-MST can promote the persulfidation of specificity protein 1 (SP1) by producing H2S and polysulfides, thereby activating the promoter of the CYR61 gene and increasing the level of CYR61 in colon cancer cells." (PMID 39813769, 2025). "In human colon carcinoma HT29 cells, butyrate dephosphorylates and acetylates Sp1 through Ser/Thr phosphatases, resulting in reduced binding between Sp1 and TLR5 promoter." (PMID 39228402, 2024).
colon carcinoma (continued). "Subsequently, we uncovered two potential reasons for the lower expression of GSTM2 in colon cancer tissues, including the deep deletion of GSTM2 on genome, and the up-regulation of RAD21 or SP1." (PMID 36263204, 2022). "Treatment with TS (250 μg/ml) significantly induced the up-regulation of Sp1 and CHOP transcription factors in human colon cancer cell lines." (PMID 34543231, 2021). "Specifically, in human colon carcinoma cells, the authors showed that deacetylation of SP1 by HDAC3 results in increased binding of SP1 to the EGFR promoter." (PMID 26243279, 2015). "In colon cancer, HDAC inhibitors can induce cancer cell apoptosis by activating Krüppel-like factor 4, and Sp1/Sp3 can increase the apoptotic sensitivity of colon cancers to histone deacetylase inhibitors." (PMID 23148884, 2012). "In chemoresistant colon cancer cells, upregulation of TLR2/6 and TLR5 result in downregulation of miR-125b-5p and upregulation of CD248 through NF-κB activation of specific protein 1 (Sp1)." (PMID 39867908, 2024). "It is reported that suppression of sp1 expression reduced the growth of colon cancer stem cells (CCSC) and induced apoptosis in vitro and in nude mouse xenografts, and the proportion of CCSC markers, CD44+/CD166+, was decreased following sp1 knock-down." (PMID 31614732, 2019). "SP1 and SP4 are essential for colon cancer cells and knockdown of them may induce apoptosis in cancer cells." (PMID 31500382, 2019). "Sp1 also interacts with Smad and promotes MMP11 expression in colon cancer cells." (PMID 29215776, 2018). "Sp1 had the highest representation among the transcription factors, in line with DIG-MSK effects on Sp1-activated gene expression in human colon carcinoma cells, and consistent with the fact that Sp1 and the mithramycin analogues bind preferentially to C/G-rich regions in DNA." (PMID 25110883, 2014). "Moreover, knockdown of Sp1, Sp3 and Sp4 (in combination) in RKO colon cancer cells also decreased expression of EGFR, cyclin D1, p65 and PTTG-1, confirming the role of Sp transcription factors in regulating expression of these genes." (PMID 21864401, 2011). "However, gel shift assays revealed an increase in Sp1 and Sp2 binding compared to sensitive cells in methotrexate-resistant HT29 human colon cancer cells, without differences in the Sp1 protein levels." (PMID 25073972, 2014). "Moreover combined knockdown of Sp1, Sp3 and Sp4 using an oligonucleotide cocktail (iSp) also decreased expression of p65, PTTG-1, EGFR and cyclin D1 in RKO cells confirming their regulation by Sp transcription factors in colon cancer cells." (PMID 21864401, 2011). "First, the SP1 motif is necessary for MACC1-mediated MET expression in colon cancer cells, which suggests that MACC1 regulation of MET requires involvement with SP1; in terms of this, MACC1 may not interact with SP1 and therefore does not regulate pancreatic cancer metastasis via the MET pathway." (PMID 36333284, 2022).